CSF1R (colony stimulating factor 1 receptor)
Diseases named in the same sentence as CSF1R in open-access papers (continued):
Sharing a sentence is not in itself a finding about the gene and the disease.
Cachexia (2 papers, 2020 to 2022). Severe weight loss, wasting of muscle, loss of appetite, and general debility related to a chronic disease. "Recently, our group demonstrated that removal of all microglia by delivery of CSF1R inhibitors worsens the outcome of cachexia and we concluded that microglia are therefore neuroprotective, although the mechanism remained elusive." (PMID 35031523, 2022). "Microglia depletion through CSF1‐R antagonism resulted in accelerated cachexia onset and increased anorexia, fatigue, and muscle catabolism during PDAC." (PMID 32039522, 2020). "Microglia depletion with an oral CSF‐1R antagonist worsened cachexia, including increased anorexia, fatigue, and muscle catabolism." (PMID 32039522, 2020).
chronic kidney disease (2 papers, 2018 to 2022). Impairment of the renal function secondary to chronic kidney damage persisting for three or more months. "Interleukin 34 (IL-34), an additional ligand of colony stimulating factor-1 receptor (CSF-1R), has been identified as a biomarker of coronary artery disease (CAD) and chronic kidney disease (CKD)." (PMID 30050466, 2018).
clear cell renal cell carcinoma (2 papers, 2022 to 2024). "Moreover, three genetic changes in CSF-1R sequence, including mutations in exon 7 and exon 22, were identified in clear renal cell cancer." (PMID 38254773, 2024). "FISH analysis indicated a copy number gain of CSF-1R in 59% of clear cell renal cell carcinoma samples." (PMID 38254773, 2024).
coronary artery disease (2 papers, 2018). "Furthermore, in vivo knockdown of CSF-1R and monocyte depletion with nanoparticle-encapsulated siRNA has recently been demonstrated for ischemic heart disease." (PMID 30349538, 2018).
corticobasal syndrome (2 papers, 2013). Corticobasal syndrome (CBS) is a rare neurodegenerative disease characterized by multifaceted motor system dysfunctions and cognitive defects such as asymmetric rigidity, bradykinesia, limb apraxia, and visuospatial dysfunction. "The CSF1R (a microglial receptor) where malfunctioning is associated with a corticobasal syndrome called hereditary diffuse leukoencephalopathy with spheroids was reported to be cosignaling with TYROBP." (PMID 23662159, 2013). "Patients with a partial loss of function of Colony-stimulating factor 1 receptor (CSF1R), which like TREM2 is a microglial receptor that signals via DAP12, have a corticobasal syndrome called hereditary diffuse leukoencephalopathy with spheroids." (PMID 24223593, 2013).
gout (2 papers, 2025 to 2026). A condition characterized by painful swelling of the joints, which is caused by deposition of urate crystals. "Experimental validation confirmed these findings: qPCR analysis demonstrated that the mRNA levels of JAK1, CSF1R, and NAMPT were significantly elevated in cellular models simulating both gout and MetS conditions." (PMID 42063773, 2026).
Hearing impairment (2 papers, 2022 to 2024). A decreased magnitude of the sensory perception of sound. "Microglia play a pivotal role in auditory brainstem formation and loss of microglia through CSF1R inhibition results in hearing impairments such as higher ABR thresholds and delayed peak latencies." (PMID 39416682, 2024).
heart failure (2 papers, 2023 to 2024). Inability of the heart to pump blood at an adequate rate to meet tissue metabolic requirements. "In line with our findings, depletion of macrophages by anti-CSF1R treatment was associated with worsened cardiac function in a model of pressure overload induced heart failure." (PMID 38775664, 2024). "MRNA levels of three candidate genes (Ccr5, Csf1r, and Tlr7) were significantly increased in heart failure mice." (PMID 38104081, 2023).
Histiocytosis (2 papers, 2023 to 2024). An excessive number of histiocytes (tissue macrophages). "Other signaling pathways for which we have specific inhibitors (AKT/mTOR, ALK, and CSF1R) now pave the way for targeted therapies rather than conventional chemotherapy regimens in adult clonal histiocytosis." (PMID 37809108, 2023).
Infertility (2 papers, 2018 to 2023). "Csf1r−/− rats survived well into adulthood with postnatal growth retardation, distinct skeletal and bone marrow abnormalities, infertility, and loss of visceral adipose tissue." (PMID 30249809, 2018). "The size difference between Csf1r−/− females and adult male wild type rats precluded test mating on welfare grounds, but the females are also likely to be infertile." (PMID 30249809, 2018).
Intestinal tumors (2 papers, 2022 to 2026). "Intestinal tumors in myeloid Mir34a-deficient mice showed elevated expression of several known Mir34a target mRNAs, including Csf1r, Pd-l1, Mmp9, Ccl22, and c-Myc." (PMID 42140945, 2026). "When the entire small intestinal tract from 18 weeks old ApcMin/+ mice was examined, Csf1r-deficient ApcMin/+ mice showed a significantly reduced number of intestinal tumors, whereas Mir34a-deficient mice showed a dramatic increase in tumor numbers." (PMID 36147476, 2022). "Taken together, the effects of the single deletions of Mir34a and Csf1r were neutralized by simultaneous inactivation of both genes, implying that Mir34a and Csf1r functionally antagonize each other during intestinal tumor formation and progression." (PMID 36147476, 2022). "In order to determine, whether inactivation of Mir34a affects intestinal tumor formation in a Csf1r-dependent manner, we generated ApcMin/+ mice with inactivation of Mir34a, Csf1r or of both genes in IECs." (PMID 36147476, 2022). "Notably, ApcMin/+ mice with deletion of both Mir34a and Csf1r displayed similar frequencies of intestinal tumors as Csf1rfl/fl;Mir34afl/fl;ApcMin/+ mice." (PMID 36147476, 2022).
monocytopenia (2 papers, 2012 to 2016). "Interestingly, treatment with GW2580 attenuated the influx of macrophages into the nerve, which was partly caused by the monocytopenia induced by CSF1R inhibition." (PMID 27174644, 2016). "Although APPSwe/PS1 mice exhibited with aging a significant monocytopenia, their bone marrow cells are still able to respond properly to M-CSF treatment, suggesting a functional CSF1-R." (PMID 23125823, 2012). "Interestingly, we found that GW2580 treatment reduced the number of macrophages recruited to the peripheral nerves of SOD1G93A mice before microgliosis occurred, which was likely due to the monocytopenia induced by CSF1R inhibition." (PMID 27174644, 2016). "CSF1R has a key role in triggering hematopoietic stem cells to differentiate into monocytes, we thus assessed whether the reduced infiltration of macrophages into the nerve induced by GW2580 treatment of SOD1 mice was due to monocytopenia." (PMID 27174644, 2016).
myocarditis (2 papers, 2018 to 2024). Myocarditis is a condition that is characterized by inflammation of the heart muscle (myocardium). "Our data indicate a pronounced up-regulation particularly of CSF-1 and CSF-1R in endomyocardial specimen from patients with myocarditis/inflammatory cardiomyopathy." (PMID 30349538, 2018).
neurofibroma (2 papers, 2017 to 2021). An intraneural or extraneural neoplasm arising from nerve tissues and neural sheaths. "Animal studies also showed that depletion of macrophages by PLX3397, which is a selective colony-stimulating factor-1 receptor (c-Fms) and c-KIT inhibitor that inhibits macrophage and mast cells recruitment, decreased the growth of neurofibroma." (PMID 34359780, 2021). "Since CSF1 is a known macrophage chemoattractant and an interaction between CSF1 and is receptor CSF1R (FMS/CD115) was identified in our microarray data analysis, we tested if an anti-CSF1 function-blocking antibody might reduce macrophage migration stimulated by neurofibroma SC conditioned medium." (PMID 28256556, 2017).
non-Hodgkin lymphoma (2 papers, 2015 to 2018). Distinct from Hodgkin lymphoma both morphologically and biologically, non-Hodgkin lymphoma (NHL) is characterized by the absence of Reed-Sternberg cells, can occur at any age, and usually presents as a localized or generalized lymphadenopathy associated with fever and weight loss. "For example, LAMs, which highly express CSF1R, have been found to support Hodgkin and non-Hodgkin’s lymphoma." (PMID 29872489, 2018).
Onset (2 papers, 2018 to 2024). The age group in which disease manifestations appear. "Nevertheless, our study suggests a potential pathogenic link between NOTCH3, CSF1R, and sporadic late-onset AD, which warrants further investigation." (PMID 29544907, 2018).
ovarian tumors (2 papers, 2024 to 2025). "This possibility is supported by evidence from syngeneic ovarian tumors, where combining chemotherapy with a CSF1R inhibitor (AZD7507) resulted in a decline in antitumor efficacy compared to chemotherapy alone." (PMID 39044819, 2024). "Another macrophage-directed strategy involves CSF-1 receptor (CSF1R) inhibition, which reduces the immunosuppressive TAM population within ovarian tumors." (PMID 40643516, 2025).
peripheral nerve injury (2 papers, 2016 to 2024). Injury to a peripheral nerve. "Hub gene Csf1 within module 2, is a cytokine that has been demonstrated the most critical contributor to macrophages expansion in DRG after peripheral nerve injury by acting via Csf1 receptor (Csf1r, within module 2) expressed on macrophages." (PMID 38813203, 2024).
preeclampsia (2 papers, 2023 to 2025). Preeclampsia is a hypertensive disorder of pregnancy that is characterized by new-onset hypertension with proteinuria presenting after 20 weeks of gestation, and depending on mild or severe forms may initially present with severe headache, visual disturbances, and hyperreflexia. "CSF1 signaling via CSF1R promotes the growth, proliferation and migration of trophoblasts in humans and mice, and high CSF1 levels are correlated with preeclampsia development." (PMID 37012406, 2023).
psoriasis (2 papers, 2021 to 2026). An autoimmune condition characterized by red, well-delineated plaques with silvery scales that are usually on the extensor surfaces and scalp. "Rationale: Psoriasis features persistent activation of the mononuclear phagocyte system (MPS), yet the subset-specific pathogenic roles of colony-stimulating factor 1 receptor (CSF1R) remain undefined." (PMID 41695464, 2026). "The depletions of macrophages by clodronate liposomes and colony stimulating factor 1 receptor (CSF-1R) inhibitor were reported to inhibit the inflammatory responses in animals with imiquimod and IL-23-induced psoriasis." (PMID 34371756, 2021).
renal fibrosis (2 papers, 2019 to 2024). A final common manifestation of a wide variety of chronic kidney diseases characterized by glomerulosclerosis and tubulointerstitial fibrosis. "Treml4_Mono and Fn1_Mac expressed a variety of similar chemokines, such as Csf1r, Lrp1, Ccl6, and Tgfb1, and the latter protein promoted early repair but was involved in renal fibrosis during the progression of AKI-CKD." (PMID 38258908, 2024).
retinal ischemia (2 papers, 2024 to 2025). A ischemic disease that involves the retina. "We used an approach for microglia depletion with the CSF-1R inhibitor PLX5622 (PLX) in the retinal ischemia-reperfusion (IR) model." (PMID 39182142, 2024).
sarcoidosis (2 papers, 2022 to 2024). Sarcoidosis is a multisystemic disorder of unknown cause characterized by the formation of immune granulomas in involved organs. "Meanwhile, the “hsa04060: cytokine–cytokine receptor interaction’ pathway, including the CCL4, CSF1R, CXCR4, FLT1, and IL7 genes, could be highly associated with immune regulation and is strongly suspected to be involved in the pathogenesis of sarcoidosis." (PMID 35860586, 2022). "Furthermore, non-synonymous SNPs in LILRB2, GZMB, APOL1, CNN2, SWAP70, and CSF1R were shown in over 50% of sarcoidosis patients." (PMID 35860586, 2022).
Sjögren’s syndrome (2 papers, 2016 to 2025). "Evidence suggests that CSF1R significantly contributes to the pathogenesis of Sjögren’s syndrome, with mutations or aberrant expression potentially inducing macrophage dysfunction, intensifying inflammatory responses, and promoting tissue damage." (PMID 40809841, 2025).
soft tissue sarcoma (2 papers, 2012 to 2022). A malignant neoplasm arising from muscle tissue, adipose tissue, blood vessels, fibrous tissue, or other supportive tissues excluding the bones. "In addition, a previous study on soft tissue sarcomas showed that macrophage colony-stimulating factor-1 receptor (CSF1R) responses were more frequent in TLSs compared with tumor tissue without TLSs." (PMID 36497450, 2022).
Splenomegaly (2 papers, 2011 to 2018). Abnormal increased size of the spleen. "Both Csf1r-MCM+;E76K mutant cohorts had splenomegaly and a small number of animals died with enlarged thymuses." (PMID 29774106, 2018).
synucleinopathy (2 papers, 2023 to 2024). A neurodegenerative disease that is characterized by the abnormal accumulation of aggregates of alpha-synuclein protein in neurons, nerve fibers or glial cells. "Further investigation into the effects of CSF1R inhibitor treatment within the LPS-only treated group could yield valuable insight into whether microglial activity propels neurodegeneration, or if synucleinopathy plays a partial or intermediary role in the process of neurodegeneration." (PMID 38302446, 2024).
tuberculosis (2 papers, 2015 to 2021). A chronic, recurrent infection caused by the bacterium Mycobacterium tuberculosis. "Because mice deficient in CSF-1R signaling have a global macrophage deficit and are susceptible to M. tuberculosis, we sought to use CSF-1R-deficient zebrafish to determine the role of macrophage deficiency in TB pathogenesis." (PMID 26159717, 2015).
type 2 diabetes (2 papers, 2021 to 2023). "The three most negative beta values derive from type 2 diabetes medication, for transcripts CSF1R, HMOX1, and NEK1 (p < 3.43 × 10−5)." (PMID 36771351, 2023).
ZIKV infection (2 papers, 2020 to 2023). "We then carried out the experiment with pregnant mice receiving the anti-CSF1R antibody at E6.5 and E7.5, accompanied by ZIKV infection within the window of E6.5-E8.5." (PMID 32628667, 2020). "It will be interesting to determine whether anti-CSF1R could directly reduce ZIKV infection/replication in microglia." (PMID 32628667, 2020).
acute megakaryoblastic leukemia (1 paper, 2007). Acute megakaryoblastic leukemia (AMKL) is a form of acute myeloid leukemia (AML) that occurs predominantly in childhood and particularly in children with Down syndrome (DS-AMKL). "Of significance to the work reported herein, a novel trans-fusion protein incorporating the amino-terminal region of RBM6 (breaking 21 amino acids into exon 3) with the carboxy-terminal region of colony stimulating factor 1 receptor (CSF1R) was recently reported in acute megakaryoblastic leukemia." (PMID 17908320, 2007).
alveolar soft part sarcoma (1 paper, 2023). An alveolar soft part sarcoma occurring in adults. "This is the case of ALK inhibitors such as crizotinib for inflammatory myofibroblastic tumors, antiangiogenics for the treatment of alveolar soft-part sarcoma (ASPS), crizotinib for clear-cell sarcomas, CSF-1R inhibitors in tenosynovial giant cell tumors or mTOR inhibitors in PEComa." (PMID 37958362, 2023).
Atrophy (1 paper, 2023). Any weakening or degeneration, especially through lack of use. "In addition, a minority of BANDDOS cases presented infantile hypotonia (27%) and atrophy of the optic nerve (29%), which were not reported in CSF1R-ALSP." (PMID 37349768, 2023).
autoimmune myocarditis (1 paper, 2018). Autoimmune myocarditis is an autoimmune disease that affects the heart. "Therefore, upon establishment of autoimmune myocarditis mice were treated with a nanoparticle-encapsulated siRNA that specifically targets CSF-1R." (PMID 30349538, 2018).
Bovine mastitis (1 paper, 2024). INFLAMMATION of the UDDER in cows. "In our results, genes such as TCONS_00211035, bta-miR-2415-3p, and CSF1R may play important roles in bovine mastitis." (PMID 38674399, 2024).
brain inflammation (1 paper, 2025). "In the CSF1R mutation mouse model, dysfunction of microglial cells is manifested by abnormal intercellular communication, mitochondrial deformities, and enlarged lysosomes, which exacerbate brain inflammation and form a vicious cycle of immune-inflammation-induced aging." (PMID 40893935, 2025). "The study found that in CSF1R mutant mice, the levels of inflammatory cytokines (such as IL-16 and IL-1β) were significantly elevated, indicating that microglial activation and pro-inflammatory responses exacerbate brain inflammation." (PMID 40893935, 2025).
carcinoma in situ (1 paper, 2020). "CSF-1R deposits were detected in the peritumoral tissues of carcinoma in situ in human HCC." (PMID 32760707, 2020).
cardiac sarcoidosis (1 paper, 2025). Sarcoidosis affecting the tissues of the heart. "The increased expression of CSF1R, IL7R, and IL4R in macrophages, together with the activation of their signaling cascades, suggests a critical role for these receptors in the pathogenesis of cardiac sarcoidosis." (PMID 40521183, 2025).
Cerebellar atrophy (1 paper, 2021). Cerebellar atrophy is defined as a cerebellum with initially normal structures, in a posterior fossa with normal size, which displays enlarged fissures (interfolial spaces) in comparison to the foliae secondary to loss of tissue. "Younger age at onset, Parkinsonian symptoms, reduction in the corpus callosum volume and presence of diffusion- restricted lesions were important predictors of CSF1R-positive cases whereas involuntary movements and brain stem or cerebellar atrophy were poor predictors of CSF1R-positive cases." (PMID 35185751, 2021).
Cerebral atrophy (1 paper, 2025). Atrophy (wasting, decrease in size of cells or tissue) affecting the cerebrum. "The imaging features of CSF1R-microglial encephalopathy encompass MRI-detected white matter lesions, predominantly found in the frontal-parietal lobes and periventricular regions, as well as cerebral atrophy (including corpus callosum thinning), alongside persistent high signals on DWI." (PMID 40893935, 2025).
cerebrovascular disease (1 paper, 2024). "In conclusion, we have demonstrated that expression of CSF1R/Csf1r and indices of microglial reactivity are increased and related to the extent of white matter pathology in human and mouse cerebrovascular disease." (PMID 37909242, 2024). "The present study builds on this work to show increased expression of CSF1R/Csf1r and genes related to microglia reactivity in abnormal white matter related to cerebrovascular disease both in human and in a mouse model." (PMID 37909242, 2024). "To address the functional role of the CSF1R pathway and microglial proliferation, we used a mouse model of cerebrovascular disease involving chronic cerebral hypoperfusion." (PMID 37909242, 2024). "We found that the expression of CSF1R/Csf1r and other markers indicative of increased microglial abundance are significantly elevated in damaged white matter in human cerebrovascular disease and in a clinically relevant mouse model of chronic cerebral hypoperfusion and vascular cognitive impairment." (PMID 37909242, 2024).
chordoma (1 paper, 2011). Chordomas are rare malignant tumors arising from embryonic remnants of the notochord in axial skeleton. "Histopathological features of 42 chordoma specimens, 21 primary and 21 advanced, were assessed by immunohistochemistry and fluorescent in situ hybridization (FISH) using PDGFRB, CSF1R, and EGFR probes." (PMID 22613809, 2011).
chronic heart failure (1 paper, 2016). "As an additional ligand of Colony Stimulating Factor-1 Receptor (CSF-1R), interleukin-34 (IL-34) has been identified as a pro-inflammatory cytokine participating in chronic heart failure (CHF)." (PMID 27982136, 2016).